DNAJC6-AS1 (DNAJC6 antisense RNA 1)
Synonyms: AL139294.1
Gene: Long non-coding RNA gene on chromosome 1 (65,279,456 to 65,306,521, reverse strand). Ensembl gene ENSG00000229294.
Diseases named in the same sentence as DNAJC6-AS1 in open-access papers:
DNAJC6-AS1 is named in the same sentence as 1 disease in open-access papers, as found by Europe PMC text mining. Sharing a sentence is not in itself a finding about the gene and the disease.
DNAJC6-AS1 shares sentences with these, for which no sentence is quoted: lymph node metastasis (1 paper).